IL1B (interleukin 1 beta)
Diseases named in the same sentence as IL1B in open-access papers (continued):
Sharing a sentence is not in itself a finding about the gene and the disease.
lung carcinoma (continued). "Mainly expressed in innate immune cells (i.e., monocytes, macrophages, and DCs), IL-1β demonstrates a significant facilitator in lung cancer metastasis and growth through these paracrine interactions." (PMID 38539448, 2024). "IL-1β advances lung cancer progression through numerous mechanisms including inducing angiogenic factors like VEGF, activating oncogenic signaling, and promoting immunosuppression and inflammation." (PMID 38957317, 2024). "Further, the combined IL-4 and TNF-α treatment had been found to cause synergistic augmentation in PD-L1-expression in renal carcinoma cells while the inductive effect of IL-1β on PD-L1-expression had been demonstrated in lung cancer and glioma cell lines." (PMID 39445017, 2024). "Currently, the major clinical program looking at IL-1β therapy in lung cancer is CANOPY (Canakinumab Outcomes in Patients with NSCLC Study)." (PMID 38539448, 2024). "Clinical research also confirms that inhibiting IL-1β significantly reduces the incidence rate of lung cancer in a dose-dependent manner." (PMID 38571500, 2024). "Further, inflammasome-released cytokine IL-1β has been shown to promote metastasis of lung cancer cells through adhesion, invasion, and angiogenesis processes." (PMID 39769450, 2024). "IL-1β has been found to increase metastasis in lung cancer through angiogenesis, tumor epithelial-to-mesenchymal transition, adhesion, growth invasion, and cytokine production." (PMID 38539448, 2024). "In vitro and in vivo data have indicated that IL-1β in particular promotes the migration and invasion of lung cancer cells, triggering more aggressive cancer phenotypes." (PMID 37304133, 2023). "The ROC plot analysis revealed that IL-1b, IL-2, IL-6, IL-10, IL-12p70, and TNF-alpha had a significant association with lung cancer, although with relatively low discriminative performance." (PMID 37373957, 2023). "A canakinumab (anti-IL-1β) agent trial on atherosclerosis patients revealed decreased incidence of lung cancer in these patients compared to the placebo group." (PMID 36899885, 2023). "Our study shows that IDO1 and IDO1’s product Kyn are elevated in lung cancer cells exposed to IL-1β." (PMID 37985999, 2023). "Serum IL-1β levels in lung cancer patients are notably elevated compared to those in healthy individuals, and these heightened levels are also associated with worse clinical outcomes." (PMID 37985999, 2023). "We observed that PM induces an altered progenitor state in EGFR mutant AT2 cells through the macrophage release of IL-1β, which promotes lung cancer." (PMID 37020004, 2023). "This study shows associations between serum levels of IL-6, IL-1β, and IFN-γ and lung cancer risk, underscoring the potential of these cytokines to act as risk biomarkers." (PMID 38067398, 2023). "It is notable that the antibody canakinumab, which is targeted against IL-1β, a cytokine induced in both mice and humans following PM exposure, has been shown to reduce lung cancer incidence in the cardiovascular prevention trial CANTOS43." (PMID 37020004, 2023). "Recent advancements in our understanding of the intricate relationship between inflammation and oncogenesis, particularly involving the IL-1β/PD-1/PD-L1 pathway, have shed light on their application in lung cancer development and clinical outcomes of patients." (PMID 37511306, 2023). "In contrast to the results obtained in our research, other studies obtained significantly higher values of IL-6 and IL-1β in BALF in patients with lung cancer compared to the control group." (PMID 37373987, 2023). "IL-1b and IL-6 are also markers for alveolar macrophage activity and can influence lung cancer survival prognosis." (PMID 37373957, 2023). "In conclusion, the use of DEX for 2 weeks inhibited lung cancer progression by suppressing inflammasome- and IL-1β signaling-induced inflammation and enhancing NK cell activity." (PMID 37528154, 2023).
lung carcinoma (continued). "Here, we found that PAK1 plays a key role in the IL-1β–induced migration and invasion of lung cancer cells." (PMID 38188678, 2023). "The findings stress the need for molecular stratification of current clinical trials of IL-1β inhibition against lung cancer." (PMID 36980752, 2023). "Inhibiting inflammatory cytokine IL-1β, which is elevated systemically in lung cancer patients and also within lung tumors, was effective in reducing lung cancer incidence and mortality." (PMID 37985999, 2023). "In line with previous studies, this investigation suggests the associations among serum levels of IL-6, IL-1β, and IFN-γ and the lung cancer risk, underscoring the potential of these cytokines to act as risk biomarkers." (PMID 38067398, 2023). "Inflammation plays a significant role in various cancers, including lung cancer, where the inflammatory cytokine IL-1β is often elevated in the tumor microenvironment." (PMID 37985999, 2023). "Our study demonstrates the association between serum levels of IL-6, IL-1β, and IFN-γ and the lung cancer risk." (PMID 38067398, 2023). "In lung cancer, IL1β was reported to promote tumour genesis by facilitating inflammation, invasion, and angiogenesis." (PMID 36900301, 2023). "IL-1β inhibitors, such as canakinumab, have been proven safe in lung cancer patients and have a survival benefit for certain groups." (PMID 36694200, 2023). "To gain better insights into the biological effects of IL-1β in lung cancer cells, we used the TCGA database to identify genes that are co-expressed with IDO1 in lung adenocarcinoma patients." (PMID 37985999, 2023). "The results demonstrated that treatment of lung cancer A549 cells with LPS and ATP induced the expression of IL-6 and inflammasome-related cytokines IL-1β and IL-18, as well as increased NLRP3 gene expression." (PMID 38026959, 2023). "In lung cancer, it has also been shown that commensal bacteria promote IL-1β production from local macrophages, inducing tumor cell proliferation and inflammation." (PMID 37511306, 2023). "Lowering pro-inflammatory cytokines, such as IL-1β, IL-2, IL-6, IL-8, IL-10, IL-12, interferon γ (IFN-γ), TNF-α, and granulocyte-macrophage colony-stimulating factor (CSF), can reduce lung cancer risk, particularly among smokers." (PMID 36986550, 2023). "In an in vitro model, astrocytes were shown to secrete inflammatory cytokines (IL-6, tumor necrosis factor-α (TNF-α) and IL-1β) in the presence of lung cancer cells, resulting in increased proliferation of the tumor cells." (PMID 37749707, 2023). "In this study, we found that IL‐1β significantly promoted the expression of PD‐L1 in multiple cancers, including ovarian cancer, lung cancer, and glioma." (PMID 37009412, 2023). "The IL1B three htSNPs were evaluated in a Northeastern-Chinese hospital-based case–control study involving 627 lung cancer cases and 633 controls." (PMID 37147350, 2023). "Increased IL-1β promotes lung cancer spread by triggering angiogenesis, tumor growth, invasion, adhesion, cytokine production, and tumor epithelial-to-mesenchymal transition." (PMID 36874133, 2023). "In an experiment of C3G plus 5-FU (a commonly used basic chemotherapy drug) in nude mice against lung cancer, the inflammatory cytokine, IL-1β, IL-6 and TNF-α, COX-2, NF-kpa and PCNA was decreased." (PMID 36771198, 2023). "Here we show that interleukin-1β (IL-1β) plays a key role in regulation of PD-L1 expression in non–small cell lung cancer (NSCLC)." (PMID 37441079, 2023). "LL-37 cooperated with IL-33 to increase the phosphorylation of p38 MAPK as well as NF-κB p65 pathways, and augmented IL-6 and IL-1β secretion, thus resulting in the proliferation of lung cancer cells in vitro." (PMID 35634336, 2022). "In fact, interception of IL‐1β significantly reduced the incidence of lung cancer in a clinical study, suggesting the great potential of IL1B as a new therapeutic target for GBM." (PMID 35083859, 2022).
lung carcinoma (continued). "Expectedly, in the present study, we found that BFXJY treatment relieved the up-regulation of NLRP3 inflammasome responses in lung cancer with Qi-yin deficiency, as indicated by the decrease of the serum, mRNA, and protein level of NLRP3, ASC, IL-1β, MDA." (PMID 35292015, 2022). "In vitro and in vivo studies have found IL-1β facilitates lung cancer metastasis by inducing cytokine production, angiogenesis, and tumor epithelial-to-mesenchymal transition, growth, invasion, and adhesion." (PMID 35086565, 2022). "In lung carcinoma Lewis will upregulate IL-1β and IL-6 through the p38/mitogen activated protein kinase (MAPK) pathway." (PMID 35340325, 2022). "After IL-1β activates IL-1, it participates in the related immune inflammatory response of lung cancer by activating NF-κB and other pathways." (PMID 36091125, 2022). "In this study, we found that the levels of CEA, IL-1β, IL-6, and IL-8 in the lung cancer group were significantly higher than those in the healthy group, consistent with the reports in the literature." (PMID 35928100, 2022). "The unanticipated results from the CANTOS trial together with the preclinical findings on the role of IL-1β in lung cancer have led to the design of a number of clinical trials that are currently exploring IL-1β as a therapeutic target in lung cancer." (PMID 35086565, 2022). "A recent study found elevated IL-1β serum levels in lung cancer patients correlated with the high percentage of MDSCs and led to poor survival." (PMID 35086565, 2022). "Recent clinical trials using a monoclonal antibody targeting IL-1β (canakinumab) also indicated a potential role of this cytokine in lung cancer." (PMID 36430236, 2022). "The Canakinumab Anti-inflammatory Thrombosis Outcomes Study (CANTOS) trial evaluated anti-IL-1β to treat atherosclerosis, and results indicated that treatment significantly reduced lung cancer incidence." (PMID 35565306, 2022). "We also discovered changes in the expression of new targets of FZD9, including EZH2, IL1β, and VEGFA, all of which are associated with lung cancer." (PMID 35924166, 2022). "While still pending definitive data, correlative studies and subgroup analyses from various clinical trials, we hope IL-1β inhibition opens a new avenue for lung cancer therapy through targeting pro-tumor inflammation." (PMID 35086565, 2022). "Elevated IL-1β produced by tumors from highly metastatic lung cancer cells induces macrophages to increase the expression of angiogenic and lymphangiogenic factors." (PMID 35086565, 2022). "Meanwhile, ectopic expression of P65 also rescued S phase blockage and expression of cell cycle-related genes including CDK2, Cyclin D1 and Cyclin E1, in addition to NF-κB target genes including IL-1β, IL-6 and TNFα in lung cancer cells overexpressing ZNF24." (PMID 36457047, 2022). "On this note, a markedly upregulated expression of inflammasome components, which led to IL-1β secretion, was found in human lung cancer tissue." (PMID 35086565, 2022). "Based on our findings that IL-1β blockade can strengthen antitumor cytotoxic activity in the TME, we also sought to determine the early therapeutic effects of IL-1β blockade in K-ras–mutant lung cancer." (PMID 35471938, 2022). "Across the three groups, serum levels of CEA, IL-1β, IL-6, and IL-8 were highest in the lung cancer group, and the differences among the three groups were statistically significant (p = 0.000)." (PMID 35928100, 2022). "Accordingly, we evaluated CD68 and IL-1β scores in histological lung cancer specimens from early NSCLC patients with poor survival and long survival." (PMID 35884397, 2022). "The evident pro-tumor role of this molecule is testified by several clinical trials investigating IL1β as a promising therapeutic target for the treatment of lung cancer patients." (PMID 36555441, 2022).
lung carcinoma (continued). "This has opened a promising new avenue for lung cancer therapy, and strategies using anti-IL-1β therapy alone or in combination with chemotherapy and/or immune checkpoint blockade are currently being evaluated in several clinical trials." (PMID 35086565, 2022). "Despite these insights on the potential implication of IL-1β in lung cancer clinical outcomes, the role of this proinflammatory cytokine in the early pathogenesis of KM-LUAD is poorly understood." (PMID 35471938, 2022). "Results indicated that IL-1β played a critical role in MDSCs' mediated proliferation, migration, and metastasis of lung cancer cells, which was consistent with previous studies." (PMID 34055197, 2021). "The present study investigated the mechanism of interleukin-1β (IL-1β)-induced TF expression in A549 lung cancer cells." (PMID 34205482, 2021). "Specifically, poor prognosis of lung cancer and reduced T cell activity have been observed in both IL-1β K/O and IL-1R antagonist K/O mice." (PMID 33686176, 2021). "To date, definitive evidence about the role of IL-1β in lung cancer is limited, especially in the general population." (PMID 34475499, 2021). "Suggestive direct effects were also noted for IL-1β, IL-1Ra, IL-36γ with lung cancer, IL-1α/β, IL-1Ra with LUAD, and IL-1β, IL-18BP with LUSC, after adjusting for genetically predicted effects of other IL-1 family members/receptors." (PMID 34475499, 2021). "The expression level of IL-6 was measured by IL-6 sandwich ELISA after treating human lung carcinoma cell line A549 with IL-1β and Canakinumab, pro-Canakinumab, MMP-9 pre-incubated Canakinumab or MMP-9 pre-incubated pro-Canakinumab, respectively." (PMID 34290297, 2021). "In lung cancer patients who received the NF-κB inhibitor, the serum levels of IL-1β were increased, and co-treatment of an IL-1R antagonist and the NF-κB inhibitor decreased formation of lung cancer in mice." (PMID 33686176, 2021). "Genetically predicted higher circulating IL-1β was inversely associated with LUAD and LUSC, and was suggestively associated with decreased lung cancer risk after adjusting for genetically predicted effects of IL-1α and IL-Ra, without pleiotropy identified." (PMID 34475499, 2021). "One interesting study on mice showed, that neutrophil-derived IL-1β blocks the effect of nuclear factor κB (NF-κB) inhibitors against lung cancer." (PMID 34885082, 2021). "In summary, our results suggest that IL-1β leads to increased TF formation in lung cancer cells via both Src/EGFR/p42/44 MAPK-dependent and EGFR-independent signaling pathways, with the latter mediated via p38 MAPK and JNK." (PMID 34205482, 2021). "We demonstrated that the IL-1β upregulation was more frequent in less advanced stages of lung cancer pT1 when compared with pT2 and pT3 + pT4." (PMID 33658555, 2021). "We primarily assessed the effects of genetically predicted IL-1α, IL-1β, IL-1Ra, IL-1Racp, IL-18, and IL-18BP with lung cancer and its subtypes of LUAD and LUSC, because LUAD is more common than LUSC in people of European ancestry." (PMID 34475499, 2021). "At the molecular level, mitigating IL-1β signaling would prevent the oncogenic activation of the alternative pathway of NF-κB signaling in lung cancer cells, impairing in this way the cascade initiated by KRAS mutant tumor cells." (PMID 33494181, 2021). "Results confirmed that the IL-1β/NF-κB signaling pathway was one of the key pathways of the FZQX prescription in regulating MDSCs to inhibit lung cancer progression." (PMID 34055197, 2021). "Moreover, loss of miR-708 in diseased lung cancer may contribute to uncoupled TNFα/IL-1β signaling." (PMID 33776573, 2021). "Genetically predicted higher circulating IL-1Ra was suggestively positively associated with increased risk of both lung cancer and LUAD after adjusting for genetically predicted effects of IL-1α and IL-1β." (PMID 34475499, 2021).
lung carcinoma (continued). "Except hematopoietic cells, IL-1β overexpressing lung cancer cells acquired an aggressive phenotype for cancer development by increasing the expression of ICAM-1 and matrix metalloproteinase-262." (PMID 33686176, 2021). "There was also suggestive evidence for possible associations of IL-1β, IL-1Ra, IL-36γ with lung cancer, IL-1α/β, IL-1Ra with LUAD, and IL-1β, IL-18BP with LUSC, perhaps via other IL-1 family members/receptors." (PMID 34475499, 2021). "Targeting IL-1β was one of the underlying mechanisms for the FZQX prescription in suppressing the proliferation and metastasis of lung cancer cells." (PMID 34055197, 2021). "Previous studies have shown that IL-1β secreted by macrophages, lung epithelial cells, and lung cancer cells contributed to the formation and maintenance of the tumor inflammatory environment." (PMID 34055197, 2021). "The trial revealed that specific neutralization of IL‐1β reduced the incidence of subsequent cardiovascular events and death from lung cancer." (PMID 33630761, 2021). "A recent trial suggested that Canakinumab, a fully human monoclonal antibody targeting interleukin (IL)-1β, reduced lung cancer incidence by 67% and mortality by 77%2." (PMID 34475499, 2021). "A stable isotope labeling based proteomics study was conducted to identify changes in the proteome of A549 lung cancer cells stimulated with IL-1β." (PMID 32231562, 2020). "The level of IL-1β in bronchoalveolar lavage is higher in patients with lung cancer than in patients with benign lung disease." (PMID 32635472, 2020). "Here, we further showed that lung cancer microparticles (L-MPs) induce macrophages to release a key proinflammatory cytokine, IL-1β, thus promoting lung cancer development." (PMID 31649305, 2020). "Previous research also confirms that RAs produce IL-6, tumor necrosis factor-α (TNF-α), and IL-1β, all of which promote lung cancer brain metastasis." (PMID 33262947, 2020). "In the present study, we found that treatment with TNF-α or IL-1β increases Oct4 expression in lung cancer cells through NF-κB." (PMID 32487125, 2020). "The production of CCL20 has been reported to activate MAPK and PI3K signaling pathways following IL-1β treatment of lung cancer cells." (PMID 32418112, 2020). "In lung cancer, inflammasome activity generates IL-1β and IL-8 in promoting EMT and secretion of cytokines that modulate the tumor microenvironment to promote lung cancer progression." (PMID 31685946, 2020). "Consistent with this in vitro result, IL-1β levels increased in lung cancer patients compared to the healthy controls." (PMID 31649305, 2020). "When exposed to IL-1β (1 ng/ml) for 48 hours, A549 lung cancer cells displayed a disaggregated growth pattern with increased cell protrusions, indicating a mesenchymal phenotype." (PMID 31941995, 2020). "The immunohistochemical staining analysis also showed that IL-1β was present in patients’ lung cancer tissues." (PMID 31649305, 2020). "In lung cancer for instance, certain cytokines (IL-4, IL-5, IL-8, IL-10, IFN-γ, and TNF-α) were significantly elevated among EA compared to AA patients, whereas elevated IL-1β, IL-10, and TNF-α levels were associated with lung cancer only among AA patients." (PMID 32714862, 2020). "Together, these results suggest that hL-MP-affected macrophages promote human lung cancer development via secretion of IL-1β." (PMID 31649305, 2020). "After PM10 exposure for 24 h, mRNA expression of the pro-inflammatory cytokines including TNF-α (5.5-fold) and IL-1β (8.8-fold) were increased in A549 lung cancer cells." (PMID 33374928, 2020). "A study on silica-promoted lung cancer shows that there was an exponential increase in the number of lung tumors per mouse with increasing expression IL-1β in the lungs." (PMID 32778128, 2020). "Recently, strategies aimed at targeting IL-1β signaling pathway using a blocking antibody have unexpectedly shown great promise on incident lung cancer." (PMID 30832375, 2019).